ENSG00000252193
Synonyms: LOC124900461
Gene: Small Cajal body-specific RNA gene on chromosome 20 (43,304,555 to 43,304,679, forward strand). Ensembl gene ENSG00000252193.
Gene Ontology:
Biological process: RNA processing
Cellular component: Cajal body; nucleolus